BRAF (B-Raf proto-oncogene, serine/threonine kinase)
Diseases named in the same sentence as BRAF in open-access papers (continued):
Sharing a sentence is not in itself a finding about the gene and the disease.
tumor (continued). "The concept scores of mucus, stroma, and tumor regions for BRAF mutation with c.1799T > A (p.V600E) detection are 19.89, 18.94, and 16.87, respectively." (PMID 37055393, 2023). "If a loss of MLH1 and PMS2 is detected by IHC in tumor tissue, the additional presence of a BRAF V600E variant in tumor tissue or of promotor methylation of MLH1 likely indicates a sporadic CRC case." (PMID 36760167, 2023). "Tumour sidedness has also been shown to affect the rate of BRAF mutation in this study, with proximal (right-sided) tumours manifesting higher rates." (PMID 37240418, 2023). "Within the training cohort, univariable analysis demonstrated that sex, HT, tumor size, tumor number, extrathyroidal extension, BRAF mutation, TERT promoter mutations and NRAS mutations were relative influencing factors of CLNM (P<0.05)." (PMID 36817603, 2023). "It was also indicated that BRAF V600E mutation was a potential anti-tumor target of apatinib for the first time." (PMID 36759818, 2023). "Some genes, such as the NHLRC4 gene (ubiquitin protein ligase activity) showed differential methylation (hypomethylation) in tumor tissue that was greater in the presence of BRAF mutation compared to wild-type patients." (PMID 36975440, 2023). "The width of the resection margins is discussed controversially, especially concerning neoadjuvant chemotherapy, size of the primary tumor and BRAF/KRAS mutation." (PMID 36922643, 2023). "Both BRAF-mutated patients had some decrease in tumor size following redifferentiation therapy (one PR and one SD)." (PMID 37435488, 2023). "These medications work by blocking the activity of the mutated BRAF protein, effectively hindering its signaling cascade and impeding tumor growth." (PMID 38021761, 2023). "Out of options for additional treatments, next-generation sequencing on a lung biopsy revealed that the tumor contained a BRAF V600E mutation." (PMID 37627272, 2023). "The tumor suppressor genes affected by the 10q deletions in BRAF-mutated tumors include those located at 10q11-23 (RASSF4, C10orf99, and PTEN) and at 10q26 (DMBT1, C10orf90)." (PMID 37761808, 2023). "Thirty-six tumor samples from 19 BRAF V600+ and 17 BRAF V600− patients (three of whom had pathogenetic mutations in the KIT gene) were analyzed and their mutational profiles/CNV/LOH correlated with clinical response." (PMID 36901733, 2023). "The primary cause affecting the prognosis of PTC include age, tumor size, extrathyroidal extension, lymph node metastasis, distant metastasis, BRAF mutation, TERT mutation, and so on." (PMID 36353231, 2022). "To better understand the potential role of BRAF mutation in anti-tumor immunity in the NSCLC microenvironment, we analyzed a series of genes related to the significant immune pathways." (PMID 36543792, 2022). "The blue line represents the KRAS-mutated tumours (mutKRAS) and the green dotted line represents the BRAF-mutated (mutBRAF) tumours." (PMID 34887523, 2022). "The two cases of BRAF K601E mutation were both in borderline tumours: one for NIFTP and the other for WT‐UMP." (PMID 35247035, 2022). "Immunostaining for BRAF VE1 showed diffuse moderate cytoplasmic expression in tumor cells, which is predictive of BRAF V600E mutation." (PMID 35945543, 2022). "Intriguingly, some HDACI, including sodium butyrate and SAHA, have been shown to sensitize tumor cells bearing the BRAF-V600E mutation to the effect of vemurafenib." (PMID 36009541, 2022). "Patient 3 is a 55-year-old Caucasian female with BRAF wild type cutaneous metastatic melanoma (tumor mutation burden 4 mutations/megabase), aortic stenosis, and severe pulmonary hypertension." (PMID 36045435, 2022).
tumor (continued). "The pathologist reviewed 104 tumors with BRAF mutation and analyzed the immune-related pathologic variables using 98 tumor tissues, except for 6 tumors unavailable for multiplex IHC." (PMID 35625987, 2022). "The blue line represents the KRAS-mutated tumours (mutKRAS) tumours and the green dotted line represents the BRAF-mutated microsatellite stable (MSS) (mutBRAF/MSS) tumours." (PMID 34887523, 2022). "Based on a preoperative determination of tumor size (T status), multifocality, and the BRAF V600E mutation, elective central neck compartment dissection can be advocated for high-risk patients." (PMID 36672561, 2022). "Activating mutations of Ras GTPases, which are the upstream activators of RAF1, occur in about 19% of human neoplasms, and BRAF is mutated in about 7% of all cancers." (PMID 35203304, 2022). "BRAF mutations were identified in 6 samples (7.5%): two harbored V600E, one tumor each for K601E, T599K and T310I mutations, and the final tumor carried both G596D and E451K mutations." (PMID 35747820, 2022). "When analysing levels of P. micra and F. nucleatum in tumour tissue in relation to tumour molecular features, high levels of both bacteria were found to be associated with BRAF-mutated tumours and tumours of the MSI subtype." (PMID 36497419, 2022). "Predictors of LNM in PTC are well known, including larger tumor size, extracapsular invasion, and BRAF mutation." (PMID 36009596, 2022). "The cohort included 72 patients with a primary diagnosis of mCRC, with evidence of RAS/BRAF mutations in both primary tumor tissue and plasma samples collected before starting first line treatments." (PMID 35159069, 2022). "The aim of our study was to evaluate the clinical utility of plasma circulating tumor DNA analysis for BRAF mutation." (PMID 35159044, 2022). "Activation of the MAPK signaling pathway as a result of mutations occurring in the RAS and BRAF genes can lead to rapid tumor progression and poor prognosis of ATC." (PMID 36482411, 2022). "MUC5AC was additionally associated with right-sided tumor location (p = 0.01), higher pT (p = 0.0073), more frequent distant metastasis (p = 0.0334), higher tumor grade (p < 0.0001), frequent BRAF mutation (p < 0.0001) and MMR-deficiency (p < 0.0001)." (PMID 34475526, 2022). "The multivariate logistic analysis showed that Age (p < 0.001), Gender (p < 0.001), Multifocality (p < 0.001), BRAF (p = 0.027), and Tumor size (p < 0.001) were associated with CLNM." (PMID 35784530, 2022). "BRAF mutated cancers evaluated from primary tumor biopsy showed MSI high in 51.9% of samples while in BRAF mutated cancers evaluated from metastatic site biopsies showed MSI high in 11.5% of samples (Fisher’s exact test p = 0.02)." (PMID 36079062, 2022). "Multivariate logistic analysis showed that Age (OR 0.947–0.966), Gender (OR 1.541–2.589), Multifocality (OR 2.348–3.815), BRAF (OR 1.044–1.926), and Tumor size (OR 4.127–6.416) were associated with CLNM." (PMID 35784530, 2022). "The positive association between BRAF V600E mutation with MSI-h/dMMR tumours is well documented, as well as the mutual exclusivity with KRAS mutation." (PMID 36819812, 2022). "Here, we performed Nanostring-panel RNA sequencing of 57 BRAF-mutated and wild-type tumor tissue specimens to explore the immune microenvironment." (PMID 36543792, 2022). "We compared the clinicopathological characteristics, microsatellite instability status, BRAF classification, and tumor mutation burden of patients harboring the double mutants with those of patients harboring KRAS or BRAF single mutations." (PMID 35280113, 2022). "Even the presence of genetic mutations in tumor RAS or BRAF sequences and MSI status cannot always predict the therapeutic response in mCRC patients." (PMID 36011003, 2022).
tumor (continued). "The KRAS G12/G13 mutation was ubiquitous and the NRAS G12/G13 mutation coexisted in the tumor samples we analyzed with the presence of BRAF mutation (AF‰ ≥ 1)." (PMID 35681771, 2022). "Most notably, BRAF + MEK inhibition is associated with an influx of T cells into the tumor microenvironment in patients." (PMID 35444175, 2022). "According to recent studies, the possible mechanisms is partly due to the modulation of the tumor microenvironment, the induction of immune responses and the presence and low frequency of BRAF mutations." (PMID 35359359, 2022). "BRAF V600E mutated GBM presents its clinical-pathological features including epithelioid features of the tumor cell." (PMID 36686797, 2022). "If the tumor harbors a BRAF mutation, it is PTC derived, and the prognosis is the most favorable of all types of ATC." (PMID 35692397, 2022). "Of interest, inhibition of USP9X activity by the small-molecule inhibitor DUB G9 also appears to have susceptibility to tumor growth in NRAS mutant lines compared to BRAF lines in vivo and in vitro." (PMID 35884430, 2022). "In vivo, while the control cancer cells induced tumor formation in nude mice, silencing of Furin (KO) reduced the ability of cells with KRAS or BRAF mutation to induce tumor growth." (PMID 35267511, 2022). "The blue line represents the KRAS-mutated tumours (mutKRAS) tumours and the grey dotted line represents the BRAF-mutated microsatellite stable (MSS) (mutBRAF/MSS) tumours." (PMID 34887523, 2022). "The clinical characteristics of PTC patients by tumor size and BRAF V600E mutation status (n = 287)." (PMID 35197932, 2022). "BRAF V600E-mutation in primary tumor associated with abundance of solid structures (p = 0.011) and with a tendency for less MIPs (p = 0.099)." (PMID 36018456, 2022). "A meta-analysis of 2470 PTCs showed that BRAF mutant had a higher recurrence rate than BRAF wild type (24.9% vs. 12.6%), and its sensitivity for predicting tumor recurrence was 65%, indicating that BRAF mutation is closely related to tumor recurrence." (PMID 35647194, 2022). "Patients with tumour BRAF mutations are less likely to present with liver limited metastasis (41% vs 63%), but these mutations are more often associated with peritoneal involvement (26% vs 14%)." (PMID 34887523, 2022). "RELATIVITY-047 contained patients with a higher percentage of the BRAF mutation and tumor PD-L1 positive status." (PMID 36291763, 2022). "The BRAF V595E mutation was found in almost 73% of the plasma of dogs with tumour and the concentration increased with disease progression." (PMID 35815441, 2022). "Risk factors that affect the risk of recurrence in PTC include extrathyroidal extension, lymph node involvement, BRAF mutation status, tumor size, and sex." (PMID 35550582, 2022). "We collated a total of 159 tumor samples bearing BRAF mutations, 133 with NRAS mutations, 303 with KRAS mutations, and 96 with EGFR mutations from the URMC NGS database from June 2020 to July 2021." (PMID 35627184, 2022). "BRAF-mutated tumours were more likely to be right-sided (65%) than BRAF wild-type tumours (31%, p = 0.033)." (PMID 34877621, 2022). "The MAPK pathway is frequently dysfunctional in many human cancers, the most common alterations being RAS and BRAF mutations (22% and 7% of all human tumours, respectively)." (PMID 36230797, 2022). "The aim of our study was to evaluate the clinical utility of plasma circulating tumor DNA analysis for BRAF mutation testing and to assess outcomes of therapy with BRAF/MEK inhibitors initiated based on the liquid biopsy results." (PMID 35159044, 2022). "Another prospective phase II trial evaluated FOLFOXIRI-bevacizumab in a group of 57 patients with mCRC, of which 10 had mutated BRAF tumours." (PMID 36819812, 2022). "Of these, one tumor had combination of pTERT and BRAF V600E mutations and was initially diagnosed as epithelioid GBM." (PMID 35012690, 2022).
tumor (continued). "In particular, several clinicopathological features, such as seizure onset, tumor progression, and postoperative seizure outcome, have been investigated in relation to BRAF mutations." (PMID 36699536, 2022). "This is unexpected since a recent study using cell line panels predicted that BRAF-mutated tumor cells would be likely the most sensitive to MEKi." (PMID 35272617, 2022). "Response to treatment with BRAF inhibitors (BRAFi) is extremely dependent on the origin of the BRAF mutated tumor." (PMID 36527039, 2022). "One tumor with initial histological diagnosis GBM had BRAF V600E mutation and the rest were pTERT- and BRAF V600E-wildtype." (PMID 35012690, 2022). "In BRAF V600E mutated patients, as long as systemic targeted therapies and immunotherapies are under development, liver resection is, with primary tumor resection, the only prognosis factor for overall survival." (PMID 35461290, 2022). "The multivariate Cox regression model analyzed clinicopathological features (including age, gender, neoplastic disease stage, metastasis stage, lymph node stage, tumor stage, and BRAF mutation) and risk score for each group." (PMID 35634509, 2022). "Testing for BRAF mutation status is usually performed on the most recently resected or biopsied tumours." (PMID 35080260, 2022). "As in the case of the NRAS Q61 mutation, the BRAF mutation correlates with tumor invasiveness limited to the submucosa and the right-side colon localization, the latter association being weaker than in the case of NRAS mutations." (PMID 35681771, 2022). "In this study, we used the TCGA dataset, covering 10,967 tumor samples across 32 cancer types, to analyze BRAF abnormal expression, DNA methylation, alterations (mutations and amplification/deletion), and their associations with patient survival." (PMID 35910024, 2022). "Mutations in the NF1 gene are also present in the tumor DNA of patients primarily resistant to BRAF inhibitors and patients with early or acquired resistance to these drugs." (PMID 35565444, 2022). "As with P. micra, high levels of F. nucleatum were significantly associated with age, as well as BRAF-mutated tumours and tumours of the MSI subtype." (PMID 36497419, 2022). "While BRAF V600 mutations appear to have an overall more prominent role of kinase activity for tumor growth, non-V600 BRAF mutations show great differences in kinase activation and, hence, response to BRAF plus MEK inhibition." (PMID 35380338, 2022). "Overall, BRAF mutations have been more frequently associated with a current or former smoking status and adenocarcinoma histology, although few other tumour types have been reported." (PMID 36230797, 2022). "mCRC tumours with MSI are more often BRAF mutated compared to MSS mCRC(87% vs. 16%), and mCRC patients with MSI receive less often secondary surgery." (PMID 34887523, 2022). "Imiquimod was also proposed to prolong tumor growth control by NK cells in B-Raf proto-oncogene (BRAF) mutated melanoma models treated with BRAF inhibitors." (PMID 36672572, 2022). "The additional genetic study revealed BRAF V600e mutations in both the primary tumor and a lymph node." (PMID 35233321, 2022). "In this context, a dose determination study revealed higher doses of the mutation-specific BRAF inhibitor dabrafenib to correlate with an increased expression of proliferation markers putatively contributing to tumor relapse." (PMID 35214043, 2022). "Results showed a BRAF mutation that led to a substitution of valine by glutamic acid at position 600 (V600E), in both parts of the tumor." (PMID 35725578, 2022). "It has been demonstrated that abnormal MAP-kinase pathway activation in tumor cells, due for instance, to a BRAF mutation, leads to downregulation of NIS expression." (PMID 35149914, 2022). "The option of a second surgery with the objective of a extended debulking was also considered, but when Sanger sequencing of tumor tissue identified the BRAF V600E variant, a targeted medical approach was preferred." (PMID 36447197, 2022).
tumor (continued). "In THCA, only BRAF V600E mutation was analyzed, as it is the most commonly observed genetic abnormality in this tumor." (PMID 35272691, 2022). "Heterogeneity in BRAF mutations within the same patient has been described, with differences between primary tumours and metastases, and between different metastases." (PMID 35080260, 2022). "Due to the complexity of TME and a lack of a rational mechanistic basis, it is urgent to investigate the tumor microenvironment and identify prognostic biomarkers in BRAF mutated SKCM patients." (PMID 36531226, 2022). "Searching for mutations in GIST remains necessary not only to predict a tumor’s malignancy but also to find molecular treatment targets, e.g., BRAF mutations to use BRAF inhibitors (e.g., dabrafenib) or NF1 mutations to use MEK inhibitors." (PMID 36291774, 2022). "Some of the best-studied biomarkers are: PD1/PDL1 expression, tumor mutational burden, gene expression harboring significant mutations (for example BRAF) or tumor infiltrating lymphocytes (TILs)." (PMID 36358912, 2022). "Liquid biopsy is arising as a promising technique for detecting BRAF mutation and for monitoring tumour response to therapy." (PMID 35160279, 2022). "The relationship of clinical invasive features and synergistic effect of tumor size and BRAF V600E mutation status by logistic regression analysis." (PMID 35197932, 2022). "Events that drive cancer initiation, such as activation of oncogenes (e.g., RAS or BRAF) or loss of tumour suppressors (e.g., PTEN), trigger OIS (in the case of PTEN loss also known as PTEN loss‐induced cellular senescence or PICS)." (PMID 36065138, 2022). "They found that CRC tumors with BRAF mutation show lower values of the derived radiomics texture features standard deviation and mean value of positive pixels of the tumor region of interest on CT images in comparison with wild-type BRAF." (PMID 35742947, 2022). "A sensitivity study was conducted for an association between tumour location (mandible versus maxilla) and BRAF V600E mutation for 12 out of 17 studies based on available data." (PMID 36428683, 2022). "In mCRC the prognosis and response to chemotherapy in patients with dMMR/MSI-H tumours is significantly influenced by the presence of somatic BRAF mutations which are associated with poor prognosis." (PMID 35574322, 2022). "Tumor markers included BRAF and KRAS mutations, microsatellite instability and CpG island methylator phenotype." (PMID 35383926, 2022). "In total, 22% (42/187) of patients with tumour MLH1 loss had missing results for both BRAF V600E and MLH1 promoter hypermethylation tests." (PMID 35509103, 2022). "The results showed that PTCs with concurrent BRAF and TERT promoter mutations were associated with tumor invasiveness and that BRAF or TERT promoter mutations were less aggressive." (PMID 35777039, 2022). "BRAF protein with V600E mutation has been demonstrated to promote tumor development by directly activating the MEK/ERK signaling pathway as a monomer independent of RAS." (PMID 36130926, 2022). "Concomitant KRAS and BRAF mutations in GI tumors are rare, occurring in less than 0.001% of cases and are associated with an aggressive tumor behavior." (PMID 35586494, 2022). "The combined use of GDC-0994 and the MEK inhibitor cobimetinib demonstrated improved anticancer efficacy in KRAS- and BRAF-mutated tumor models." (PMID 36233210, 2022). "Mutations of the BRAF proto-oncogene play a significant role in cell and tumor progression, with the BRAF V600E mutation being the most common genetic mutation of PTC." (PMID 36672561, 2022). "A recent meta-analysis in adults reported that BRAF mutations are positively associated with tumor aggressiveness." (PMID 35879379, 2022).